TMEM192 (transmembrane protein 192)
Synonyms: FLJ38482
Tractability: Antibody: its Gene Ontology location is reachable by antibodies, with high confidence; UniProt predicts a signal peptide or a membrane-spanning region. PROTAC: ubiquitination databases record sites on it; its protein half-life has been measured.
Gene: Protein-coding gene on chromosome 4 (165,070,608 to 165,208,549, reverse strand). Ensembl gene ENSG00000170088.
Subcellular location: Lysosome membrane; Late endosome
Subcellular location (Human Protein Atlas): Endosomes; Lysosomes; Nucleoplasm
Gene Ontology:
Molecular function: protein homodimerization activity
Cellular component: endoplasmic reticulum; endosome; Golgi apparatus; late endosome; lysosomal membrane; lysosome; nucleus; perinuclear region of cytoplasm; plasma membrane
Genetic constraint (gnomAD): Loss-of-function variants: 20 observed, 24.89 expected, observed/expected ratio (o/e) 0.8, 90% interval 0.56 to 1.17. The upper end of that interval is the gene's LOEUF score, 1.17, which puts it in group 5 of 6, group 1 being the genes least tolerant of losing a copy. Missense variants: 266 observed, 294.42 expected, observed/expected ratio (o/e) 0.9, 90% interval 0.82 to 1. Synonymous variants: 98 observed, 113.26 expected, observed/expected ratio (o/e) 0.87, 90% interval 0.73 to 1.02.
Homologues: Orthologues: chimpanzee TMEM192 (99% identical), macaque TMEM192 (95% identical), rabbit TMEM192 (85% identical), pig TMEM192 (82% identical), dog TMEM192 (79% identical), mouse Tmem192 (77% identical), rat Tmem192 (77% identical), guinea pig TMEM192 (66% identical), tropical clawed frog tmem192 (51% identical), zebrafish tmem192 (38% identical), Drosophila melanogaster CG7523 (20% identical).
Diseases named in the same sentence as TMEM192 in open-access papers:
TMEM192 is named in the same sentence as 12 diseases in open-access papers, as found by Europe PMC text mining. Sharing a sentence is not in itself a finding about the gene and the disease. The quoted sentences say what the papers report.
Burkitt lymphoma (2 papers, 2024 to 2025). A rare form of malignant mature B-cell non-Hodgkin lymphoma. "We stably expressed TMEM192 in Rael Burkitt lymphoma B cells, in which BCAT1 and LAMP1 colocalization was increased by αIgM + CpG stimulation." (PMID 40924473, 2025). "We stably expressed TMEM192 in Rael Burkitt lymphoma Rael B-cells, in which BCAT1 and LAMP1 co-localization was increased by aIgM+CpG stimulation." (PMID 38854072, 2024).
hepatoma (2 papers, 2017 to 2025). "For instance, deficiency of TMEM192 in hepatoma HepG2 cells resulted in increased apoptosis and growth inhibition by the mitochondrial pathway through autophagy." (PMID 40438593, 2025). "Upon TMEM192 knockdown in hepatoma cells, a dysregulation of autophagy and increased apoptosis were reported." (PMID 28504966, 2017).
Batten disease (1 paper, 2025). "A recent paper exploring the proteomic changes in microglia with another LSD, Batten disease caused by loss of CLN3, identify similar changes to those seen here, including increased TTYH3, PTTG1IP, LAMTOR3, PSAP, STARD3NL, TSPAN7, TMEM192 and NPC1." (PMID 40608809, 2025).
breast carcinoma (1 paper, 2023). "Six variants had no additional breast-cancer-affected carriers identified in the pedigrees they were originally found in (in genes KIF15, TMEM192, MUC5AC, TEP1, ZFX, and TNN)." (PMID 38136396, 2023).
colon carcinoma (1 paper, 2024). "For an initial untargeted metabolomics screen, the LysoIP protocol was applied on murine colon carcinoma MC-38 WT and MFSD1−/− cells, both expressing the tagged lysosomal protein Tmem192-3xHA for lysosome immunopurification." (PMID 38507452, 2024).
pancreatic adenocarcinoma (1 paper, 2024). "Homozygous HTT KO cell lines were created using CRISPR-mediated genome editing of a pancreatic adenocarcinoma cell line PATU8988T, which stably expresses a tagged lysosomal protein, TMEM192-HA." (PMID 39074279, 2024).
tumour (3 papers, 2017 to 2022). "Altogether, this could indicate that tumour cells are more susceptible to the loss of TMEM192 than normal cells." (PMID 28504966, 2017). "In conclusion, additional studies will be required to decipher the molecular function of TMEM192 as well as its possible role in tumour cells." (PMID 28504966, 2017). "Alternatively, tumour cells may have a higher demand of the specific function of TMEM192, possibly related to their rapid proliferation or due to the upregulation of specific pathways." (PMID 28504966, 2017). "A previous study has reported that TMEM192 plays a role in supporting the growth of tumour cells." (PMID 28504966, 2017).
cancer (2 papers, 2022 to 2023). A tumor composed of atypical neoplastic, often pleomorphic cells that invade other tissues. "Interestingly, most of these genes are linked with cancer processes (Pld1, Fam13c, Svbp, TMem192, Zc3h7a, RTP4, Naa30, Zgrf1, Slc33a1, Dnmt3b, Map6, Plin4, Eps8L2, Alg12, Capg and Tdp2)." (PMID 37700325, 2023).
TMEM192 also shares sentences with these, for which no sentence is quoted: oral cancer (1 paper); ovarian tumors (1); sphingolipidoses (1); Wolman disease (1).